TET2 (tet methylcytosine dioxygenase 2)
Diseases named in the same sentence as TET2 in open-access papers (continued):
Sharing a sentence is not in itself a finding about the gene and the disease.
hepatocellular carcinoma (21 papers, 2015 to 2026). A malignant tumor that arises from hepatocytes. "In hepatocellular carcinoma, reduced TET2 levels are associated with decreased 5hmC levels and inhibition of histone acetyltransferases, resulting in excessive activation of the Akt signaling pathway." (PMID 41290745, 2025). "One of the well-documented observations is the loss of 5hmC in hepatocellular carcinoma (HCC), where reduced 5hmC levels, regulated by TET2, promote chemoresistance." (PMID 41243111, 2025). "This is because Jmjd1a expression has previously been reported to be induced by HIF-1α in several cell lines (e.g. endothelial and cancer cell lines), and Tet2 is also regulated by HIF-1α in HepG2 hepatocellular carcinoma cells." (PMID 37158274, 2023). "The decrease expression of Tet2 and Tet3 in hepatocellular carcinoma cells was accompanied by the decrease level of 5hmC, and they were up-regulated in the addition of 5-AZA." (PMID 36430235, 2022). "The upregulation of TET2 expression and the increased abundance of cytosine derivatives have also been found in hepatocellular cancer cells and human skin fibroblasts in response to 5-aza-CR44,45." (PMID 31796828, 2019). "Among the three TET genes, TET1 and TET2 expression levels have frequently been shown to be low in hepatocellular carcinoma (HCC) tissues and received most attention." (PMID 31033072, 2019). "However, the opposite findings were obtained in some cases; for example, in hepatocellular carcinoma cells, this was a knockdown of TET2 that inhibited proliferation." (PMID 37371754, 2023). "Low expression levels of TET2 have been correlated with poor prognosis in hepatocellular carcinoma." (PMID 36276976, 2022). "When we looked at the physiological functions of the TET proteins and their mechanisms of regulation of DNA methylation and transcription, out of the three TET genes TET1 and TET2, expression levels were shown to be low in hepatocellular carcinoma (HCC) tissues." (PMID 36030244, 2022). "The data presented here indicate that a drop of TET2 and TET3 expression and activity as well as IDHs is impaired in hepatocellular carcinoma with a concomitant reduction of 5hmC." (PMID 26366235, 2015). "In our study, we clearly found that only TET2 and TET3 genes are significantly reduced in HCC tissue and in hepatocellular carcinoma cell lines." (PMID 26366235, 2015). "Moreover, Sajadian underscore the impaired expression and activity of TET2 and TET3 in hepatocellular carcinoma, further validating our analysis." (PMID 39104395, 2024). "We found that TET2 expression was up‐regulated in serum‐starved hepatoma cells, while the expression of TET1 and TET3 did not change." (PMID 37752791, 2023). "A recent study showed that in hepatocellular carcinoma (HCC) cells, active DNA demethylation using a DNMT inhibitor is dependent on TET2." (PMID 27977763, 2016). "Our data clearly show that the expression and activity of TET2 and TET3 proteins but not TET1 are impaired in hepatocellular carcinoma leading to the reduction of 5hmC in HCCs." (PMID 26366235, 2015). "A study of hepatocellular carcinoma observed decreased expression of TET1, but not TET2 and TET3." (PMID 29849955, 2018).
B cell lymphoma (19 papers, 2016 to 2025). "Among the lymphoid malignancies, TET2 mutations are observed in approximately (2%) of B‐cell lymphomas and (12%) of T‐cell lymphomas." (PMID 40599235, 2025). "TET2 mutations are observed in a larger proportion of T‐cell compared to B‐cell lymphomas, loss of function TET2 mutations have been described in both, suggesting a broad lineage‐independent tumor suppressor role for TET2 in lymphomagenesis." (PMID 40116537, 2025). "One study reported that Tet2 and Tet3 deficiency increases G-quadruplex and R-loop formation and promotes B-cell lymphoma development in mice." (PMID 37363169, 2023). "Here, we elaborate a summary of TET2 mutations in the frequent co-occurrence of AITL and B-cell lymphomas (e.g., diffuse large B-cell lymphoma and classic Hodgkin lymphoma) and discuss the potential of targeting TET2 as an anti-AITL agent." (PMID 36428791, 2022). "Compared to Tet2 deficiency, Tet1/Tet2 deletion results in B-cell lymphoma with delayed disease progression." (PMID 33184433, 2020). "In additional studies, mice with a combined Tet2- and Tet3-deficiency in developing B cells developed B cell lymphoma and succumbed to disease within 5–6 months of age, much earlier than the 15–20 months observed in Tet1/Tet2-deficient mice." (PMID 29535729, 2018). "Notably, the detection of TET2 mutations in bystander B cells in AITL samples has allowed new mechanistic advances in AITL combined with B-cell lymphoma." (PMID 36428791, 2022). "Tet1-deficient mice and Tet1/Tet2 double knockout mice develop B cell lymphoma." (PMID 35805009, 2022). "One notable exception is the high incidence of TET2 somatic mutations in T‐cell lymphomas vs B‐cell lymphomas in germline mutation carriers, which may reflect differences in survival observed in Tet2 KO mouse models." (PMID 36618446, 2021). "Consequently, AITL with B-cell lymphoma is a multistep alteration, with AITL and B-cell lymphoma occurring in the T-cell zone and germinal center, following the differentiation of hematopoietic stem cells carrying the TET2 mutation into premalignant T-cell and B-cell lineages, respectively." (PMID 36428791, 2022). "In contrast, germinal center (GC)‐specific overexpression of the transcription factor Bcl6 cooperates with TET2 deletion to generate mature B‐cell lymphomas." (PMID 40599235, 2025). "Our case is distinct in that it shows the development of B-cell lymphoma and chronic MPN harboring TET2 mutations before the diagnosis of AITL." (PMID 38199781, 2023). "TET1 deletion in mouse models, both in isolation and in combination with TET2 deletion, produces B‐cell lymphomas." (PMID 36618446, 2021). "Therefore, it is likely that genetic lesions of TET2 are critical in the co-occurrence of T and B-cell lymphomas in the same patient." (PMID 36428791, 2022). "In addition, we elaborate on recent advances in AITL frequently comprising B-cell lymphoma and discuss the potential prospects of targeting TET2 as an anti-AITL agent." (PMID 36428791, 2022). "The Tet2/Tet3 deletion in developing B cells leads to B-cell lymphoma development." (PMID 33184433, 2020). "In our own studies, mice with combined early deletion of Tet2 and Tet3 in developing B cells using Mb1-Cre developed progressive B cell lymphoma and succumbed to disease within 5–6 months of age, an earlier onset compared to 15–20 months observed in Tet1/2-deficient mice." (PMID 28408905, 2017). "Moreover, all older Tet2/3 DKO mice developed B cell lymphomas with splenomegaly and lymphadenopathy by the time they were five months old." (PMID 27869616, 2016).
B cell lymphoma (continued). "Consistent with frequent TET2 mutations in DLBCL, Tet2 deletion in HSPCs or B cells in mice (using Vav-Cre or CD19-Cre) caused germinal center hyperplasia and impaired plasma cell differentiation by impairing germinal center B cell epigenome and transcriptome, ultimately developing B-cell lymphoma." (PMID 36675240, 2023). "Identifying Tet2-targeted genes/molecules in myelopoiesis and lymphomagenesis will be crucial for future studies aimed to uncover the molecular mechanisms through which Tet2 modulates hematopoiesis and serves as a tumor-suppressor gene in myelopoiesis and T/B-cell lymphomas." (PMID 33184433, 2020). "Rather, combined TET2 and TET3 loss‐of‐function in germinal centre B cells favours C‐to‐T and G‐to‐A transition mutagenesis, a finding that may be of significance for understanding the aetiology of B‐cell lymphomas evolving in conditions of reduced TET function." (PMID 31120187, 2019).
coronary artery disease (18 papers, 2019 to 2026). "Clonal hematopoiesis (CH) due to Tet methylcytosine dioxygenase 2 (TET2) driver mutations is associated with coronary heart disease and a worse prognosis for patients with aortic valve stenosis (AVS)." (PMID 41252200, 2025). "Clonal hematopoiesis, often caused by mutations in DNMT3A and TET2, is associated with blood cancer and coronary artery disease." (PMID 36097025, 2022). "CHIP-associated DNMT3A mutation was associated with a hazard ratio of 1.7 for coronary artery disease while TET2 mutation conferred a hazard ratio of 1.9." (PMID 33861346, 2021). "This multicenter study randomized approximately 28 individuals with known coronary artery disease and TET2 or DNMT3a CHIP to different combinations of DFV890, MAS825, and placebo, administered for 12 weeks, with a 30-day follow up." (PMID 39352379, 2024). "Furthermore, the trial identified specific mutations in DNMT3A, TET2, ASXL1, and JAK2 as independent contributors to heightened coronary heart disease risk." (PMID 41458386, 2025). "In a study that included subjects with coronary heart disease and controls, each major CHIP‐driving mutations, DNMT3A, TET2, ASXL1, and JAK2, was associated with an increased risk of coronary heart disease, but the hazard ratio was the lowest for the DNMT3A mutation." (PMID 36807865, 2023). "It would be worth determining whether this polymorphism impacts the outcome of TET2-mutated CHIP, including the development of coronary diseases and overt myeloid malignancies." (PMID 35115654, 2022). "Nested case–control analyses of prospective cohorts, that together enrolled 4726 participants with coronary artery disease and 3529 controls, revealed that carriers of CHIP (DNMT3A, TET2 and ASXL1 mutations) have a risk of coronary artery disease that is substantially greater than controls." (PMID 33861346, 2021). "TET2 CHIP was associated with HFpEF in both cohorts (meta-analyzed HR, 2.35 [95% CI, 1.34 to 4.11]; P = .003) independent of cardiovascular risk factors and coronary artery disease." (PMID 38270950, 2024). "Furthermore, TET2 CHIP has been identified as an independent risk factor for HFpEF, independent of conventional cardiovascular risk factors and coronary artery disease." (PMID 38985383, 2024).
gastric cancer (18 papers, 2016 to 2025). A primary or metastatic malignant neoplasm involving the stomach. "Since ANRIL is upregulated in gastric cancer and it is associated with a poor prognosis, it inversely correlates with TET2 mRNA levels." (PMID 36969033, 2023). "TET2 expression was lower in normal tissues than that in some epithelial neoplasms, such as breast adenocarcinoma and gastric cancer." (PMID 38515066, 2024). "On the other hand, TET1 and TET2 are expelled from the nucleoplasm via their nuclear export signals in gastric cancer and small intestinal neuroendocrine tumour cells, respectively." (PMID 38583183, 2024). "The ANRIL knockdown impairs the effect of TET2 on the proliferation and colony formation in gastric cancer." (PMID 36969033, 2023). "Tet Methylcytosine Dioxygenase 2 (TET2) downregulation is necessary for DNA methylation in EBV-induced gastric cancer." (PMID 35456151, 2022). "Taken together, we found a possible site-specific methylation for CD148 expression in gastric cancer, with potential regulators TET2 and TET3." (PMID 32201537, 2020). "To investigate the molecular mechanism by which extensive hypermethylation is induced in EBV-positive gastric cancer, we conducted a transcriptome analysis, and TET2 was found to be one of the downregulated genes." (PMID 27829228, 2016). "TET2 also regulates the lncRNA ANRIL by binding to its promoter in gastric cancer." (PMID 36969033, 2023). "Loss of TET2 is implicated in the development of EBV-positive nasopharyngeal carcinoma and may play a role in EBV-positive gastric carcinoma." (PMID 34893887, 2022). "In our study, only TET1 showed reduced expression in gastric cancer, while TET2 and TET3 increased in cancer tissues, an expression pattern consistent with the TCGA gastric cancer dataset." (PMID 35805009, 2022). "Moreover, curcumin was shown to upregulate the expression of both the TET2 and TET3 enzymes in gastric cancer cell lines, with consequent active demethylation and re-expression of the tumor suppressor RB1." (PMID 41516186, 2025). "In addition, EBV infection of gastric cancer cells MKN7 has been shown to downregulate TETs at the transcriptional level, especially TET2." (PMID 36980731, 2023). "Additionally, TET2 (Tet Methylcytosine Dioxygenase 2), a tumor suppressor factor responsible for CpG demethylation, decreases ANRIL expression, leading to the inhibition of gastric cancer cell growth." (PMID 37627188, 2023).
Obesity (17 papers, 2011 to 2025). Accumulation of substantial excess body fat. "They confirmed that TET2 deficiency ameliorates HFD-induced obesity and insulin resistance by partially decreasing leptin levels as well as that the expression of the leptin gene in adipocytes is regulated by TET2." (PMID 40620794, 2025). "A decrease in TET2 expression is linked to hyperleptinemia in humans with obesity, and adipocyte-specific Tet2 deficiency in mice prevents HFD-induced obesity and insulin resistance." (PMID 40862085, 2025). "Our data showed that both global and adipocyte-specific Tet2 deficiency protected against HFD-induced obesity in tandem with increased energy expenditure and decreased food intake, indicating an increase in leptin sensitivity." (PMID 38561362, 2024). "Collectively, these results indicate that Tet2 deficiency ameliorates HFD-induced obesity and insulin resistance by promoting energy consumption and inhibiting food intake." (PMID 38561362, 2024). "In conclusion, our study reveals a feedback loop between TET2 and leptin, which enables adipocytes to coordinate the hyperleptinemia associated with obesity." (PMID 38561362, 2024). "To determine the biological consequence(s) of obesity on CHIP-bearing HSC/Ps, we generated obese FBM (leptin-deficient Ob/Ob) mice possessing Tet2–/– or Dnmt3a+/– mutations to mimic the human pre-leukemic condition in the context of obesity." (PMID 37071471, 2023). "Recently, Tet2 loss-of-function mutations have been shown in mice to increase IL-1β secretion from adipose tissue and aggravate age- and obesity-related insulin resistance." (PMID 36835370, 2023). "We demonstrated that the reduction in 5-hmC associated with a decrease in TET2 expression, which reflects the inhibition of demethylation, is involved in the development of obesity-related CRC with insulin resistance and hyperglycemia." (PMID 36806702, 2023). "Together, these data suggest that obesity induced the expansion and transformation of pre-LHSCs/PCs bearing Dnmt3a or Tet2 mutations and contributed to the development of a severe MPN-like phenotype." (PMID 37071471, 2023). "Additionally, inactivating mutations of the epigenetic regulator TET2 led to metabolic dysfunction, including clonal hematopoiesis, and aggravated age- and obesity-related insulin resistance in mice." (PMID 40459008, 2025). "In addition, despite clear obesity (leptin-deficient (ob/ob) 50 g versus control 25 g), adipocytes from ob/ob mice exhibited higher gene and protein levels of TET2 than wild-type (WT) mice." (PMID 38561362, 2024). "A decrease in adipose TET2 is associated with obesity-related hyperleptinemia in humans." (PMID 38561362, 2024). "Obesity-related insulin resistance is associated with a higher incidence of TET2-CHIP." (PMID 38162500, 2023). "More interestingly, HFD-induced obesity models have been demonstrated to diminish TET2 expression in adipose endothelial cells." (PMID 40620794, 2025). "In this study, the authors treated primary differentiated adipocytes with various factors known to increase white adipose tissue concomitant with obesity and demonstrated that only leptin suppressed TET2 expression." (PMID 40620794, 2025). "In this negative feedback loop, leptin plays a predominant role, as leptin inhibits adipocyte TET2 significantly in the context of obesity." (PMID 38561362, 2024). "TET2 mRNA and protein levels were consistently and substantially decreased in adipocytes during obesity." (PMID 38561362, 2024). "To define the role of TET2 in adipocytes in regulating obesity and insulin resistance, we generated adipocyte-specific Tet2 knockout mice (AKO) by crossing Tet2fl/fl mice to Adipoq-Cre transgenic mice." (PMID 38561362, 2024). "This opened the exciting question, as to how obesity drives changes in adipose tissue TET2 expression and function." (PMID 39872508, 2024).